MIB1 (MIB E3 ubiquitin protein ligase 1)
Diseases named in the same sentence as MIB1 in open-access papers (continued):
Sharing a sentence is not in itself a finding about the gene and the disease.
pancreatic cancer (3 papers, 2021 to 2025). "To assess the association between MIB1 expression levels and pancreatic cancer clinicopathological characteristics, we evaluated MIB1 mRNA levels in the TCGA database and found that MIB1 was upregulated in 16% of pancreatic cancers." (PMID 33793053, 2021). "To elucidate the mechanisms underlying MIB1’s pro‐tumorigenic effects in pancreatic cancer, we performed immunoprecipitation and mass spectrometry to identify binding partners of MIB1." (PMID 33793053, 2021). "In this study, we show that MIB1 overexpression drives pancreatic cancer progression by targeting ST7 for proteasomal degradation." (PMID 33793053, 2021). "We also investigated the protein levels of MIB1 in pancreatic cancer specimens using tissue microarrays (n = 25 normal pancreatic tissues, n = 35 PDAC) and IHC." (PMID 33793053, 2021). "Importantly, high MIB1 expression levels in pancreatic cancer patients were associated with shorter overall survival by using The Human Protein Atlas, suggesting that aberrant MIB1 expression may represent a poor prognosis biomarker in pancreatic cancer." (PMID 33793053, 2021). "Our data suggest that MIB1 overexpression drives pancreatic cancer progression by targeting ST7 for degradation." (PMID 33793053, 2021). "Conversely, ectopic overexpression of MIB1 enhanced pancreatic cancer cell proliferation and invasion, both in BxPC‐3 and in SW1990 cells." (PMID 33793053, 2021). "The results presented herein suggest that MIB1 is a promising candidate target for pancreatic cancer therapy." (PMID 33793053, 2021). "Conversely, MIB1 overexpression decreased ST7 protein levels in pancreatic cancer cell lines, although ST7 mRNA levels remained unchanged." (PMID 33793053, 2021). "MIB1 protein levels were elevated in pancreatic cancer tissues compared with normal pancreatic tissues (P < 0.001)." (PMID 33793053, 2021). "We also evaluated the protein levels of ST7 and MIB1 in a pancreatic cancer tissue microarray (n = 35 samples)." (PMID 33793053, 2021). "Overexpression of MIB1 enhanced proliferation and invasion of pancreatic cancer cells both in vitro and in vivo." (PMID 33793053, 2021). "To assess the importance of ST7 in the tumor‐promoting effects of MIB1 in pancreatic cancer, we used BxPC‐3 cells expressing shControl, shMIB1, shST7, and shMIB1/shST7." (PMID 33793053, 2021). "We found a reverse association between MIB1 and ST7 protein levels in pancreatic cancer tissues (Pearson correlation r = −0.3535, P = 0.0372)." (PMID 33793053, 2021). "Consistently, we found that MIB1 mRNA levels were significantly higher in pancreatic tumors (n = 179) than normal pancreatic tissues (n = 171)." (PMID 33793053, 2021). "Next, we assessed MIB1’s role in pancreatic cancer cell growth." (PMID 33793053, 2021). "Our research shows that the MIB1/ST7/IQGAP1 axis is essential for pancreatic cancer progression, and MIB1 inhibition may serve as a novel therapeutic strategy in patients with pancreatic cancer." (PMID 33793053, 2021). "Although mounting evidence suggests that MIB1 is overexpressed in pancreatic tumors, the role of MIB1 in the progression of pancreatic cancer remains unclear." (PMID 33793053, 2021). "Our data demonstrated that MIB1 exerted oncogenic functions in pancreatic cancer." (PMID 33793053, 2021). "Therefore, the MIB1/ST7/IQGAP1 signaling axis is an important mediator of pancreatic cancer progression, and inhibiting MIB1 may prolong the survival of patients with pancreatic tumors." (PMID 33793053, 2021). "Finally, we show that the MIB1/ST7 axis modulates IQGAP1 expression in pancreatic cancer." (PMID 33793053, 2021). "However, the role of MIB1 in pancreatic cancer progression remains elusive." (PMID 33793053, 2021). "Importantly, we identified ST7 as a novel substrate of MIB1 in pancreatic cancer." (PMID 33793053, 2021). "In the present study, we identified that by inducing ST7 degradation, MIB1 upregulates IQGAP1 and enhances pancreatic cancer progression." (PMID 33793053, 2021).
pancreatic cancer (continued). "Together, these data indicate that MIB1 promotes ST7 polyubiquitination and proteasomal degradation in pancreatic cancer." (PMID 33793053, 2021). "Overall, these data indicate that MIB1 targets ST7 for degradation, thereby increasing IQGAP1 expression levels and promoting pancreatic cancer progression." (PMID 33793053, 2021). "In conclusion, our research shows that the MIB1/ST7/IQGAP1 axis is essential for pancreatic cancer progression, and MIB1 inhibition may serve as a novel therapeutic strategy in patients with pancreatic cancer." (PMID 33793053, 2021). "We also report that in pancreatic cancer, ST7 suppresses MIB1 expression." (PMID 33793053, 2021). "Western blot analysis of specimens from our hospital confirmed the higher MIB1 protein levels in pancreatic cancer (n = 12) than in adjacent nonmalignant tissues (n = 12)." (PMID 33793053, 2021). "Moreover, MIB1 expression levels were elevated in pancreatic cancer cell lines compared with nonmalignant pancreatic ductal epithelial cells (HDPE6‐C7)." (PMID 33793053, 2021).
pilocytic astrocytoma (3 papers, 2013 to 2024). Pilocytic astrocytoma is a rare subtype of low-grade glioma of the central nervous system characterized by a well circumscribed, often cystic, brain tumor with a discrete mural nodule and long, hair-like projections that extend from the neoplastic astrocytes. "This pilocytic astrocytoma displayed atypical features, including elevated mitotic activity and increased MIB1 proliferation index, as well as an aggressive clinical behavior with recurrence only 10 months after initial resection." (PMID 37138345, 2023). "In our study Mcm2 PIs were lower than Ki67/MIB-1 PIs and comparable with those in pilocytic astrocytomas, whereas in oligodendrogliomas the Mcm2 indices were higher." (PMID 23618321, 2013).
pituitary neoplasms (3 papers, 2013 to 2020). "It was previously documented that a nuclear antigen Ki-67 of over 3% (identified with MIB-1 antibody) exhibits a significant association with the invasiveness of pituitary tumours." (PMID 26221547, 2015). "Estimation of the cell cycle specific antigen Ki-67 by using the MIB-1 antibody has been shown to correlate with the invasiveness and prognosis of pituitary neoplasms." (PMID 24455332, 2013). "MIB-1 LI may not accurately represent pituitary tumor proliferation because the value is calculated from the highest percentage of immunoreactive tumor cells in several evaluated areas of a pituitary tumor." (PMID 32325698, 2020).
prostate carcinoma (3 papers, 2014 to 2022). A carcinoma that arises from epithelial cells of the prostate gland. "miRNA-195-5p regulates cell proliferation, migration and invasion via regulating mind bomb 1 (MIB1) in prostate cancer cells." (PMID 35457012, 2022). "Thus, MIB-1 is a reliable IHC marker of cell proliferation, and MIB-1 proliferations index (Ki-67 expression) is associated with poor prognosis in various cancers, especially breast and prostate cancer." (PMID 29246159, 2017). "With the progress of high-throughput genomics and proteomics technology, increasing prostate cancer-related tumor markers, such as MIB-1/Ki67 labeling indices, DD3, EGR-1 and Bcl-2, are constantly being discovered and used in the diagnosis and prediction of prognosis of prostate cancer." (PMID 24959274, 2014).
spinal meningioma (3 papers, 2022). Spinal meningioma isa rare type of spinal cord cancer. "The presence of a calcified spinal meningioma in CT-imaging studies was significantly linked to decreased MIB-1 labeling indices (<5%)." (PMID 36091152, 2022). "Mean +/− MIB-1 index in cranial meningiomas was 5.4 +/− 3.0, and 4.3 +/− 2.4 in spinal meningiomas, respectively (p = 0.007)." (PMID 35205781, 2022). "Spinal meningiomas have a significantly longer PFS time and differ from the cranial meningiomas regarding MIB-1 index and density of tumor-associated macrophages." (PMID 35205781, 2022). "Although previous studies are scarce, spinal meningiomas tend to have low MIB-1 indices and there is no consensus on a specific MIB-1 index cut-off value for the prediction of tumor progression or recurrence in spinal meningiomas." (PMID 36523995, 2022). "Univariable analysis revealed that spinal meningioma patients are significantly older, had a worse baseline Karnofsky Performance Status (KPS), higher acute-phase protein levels, lower incidence of WHO grade 2, lower mitotic counts, lower MIB-1 index, and less CD68+ macrophage infiltrates." (PMID 35205781, 2022).
Vestibular schwannoma (3 papers, 2019 to 2024). A vestibular schwannoma (also known as acoustic neuroma, acoustic neurinoma, or acoustic neurilemoma) is a benign, usually slow-growing tumor that develops from the VIIIth cranial nerve supplying the inner ear. "We analyzed clinical factors, imaging data and the expression of the proliferation marker MIB1 as potential influencing factors on the preoperative hearing function in a retrospective cohort of 523 primary sporadic vestibular schwannomas." (PMID 38850456, 2024). "Only a MIB1 expression equal or exceeding 1.4% was revealed as an independent marker for radiographic vestibular schwannoma growth (p = 0.0002)." (PMID 33641674, 2021). "We therefore previously performed a retrospective tissue analysis of the immunohistochemical expression of COX2 and MIB1 in 1048 vestibular schwannoma." (PMID 33641674, 2021). "A recent study by our research group demonstrated a significant association of immunohistochemical detection of COX2 and proliferative marker expression (MIB1) in a large cohort of vestibular schwannomas." (PMID 33641674, 2021). "Although the difference in MIB1 was statistically significant, the overall expression of this proliferation marker is notoriously low in a slow growing tumor like vestibular schwannoma." (PMID 33641674, 2021). "The expression of COX2 in vestibular schwannoma is associated with the preoperative tumor volume and the expression of the proliferative marker MIB1 but not with radiographic tumor growth." (PMID 33641674, 2021). "To further address this issue, we have done volumetric measurements of preoperative radiographic images to assess the preoperative tumor volume and growth rate in order to verify the proliferative impact of COX2 positive cells and MIB1 expression in vestibular schwannoma." (PMID 33641674, 2021). "However, in a case series with 15 clinically aggressive vestibular schwannomas that all showed a radiological growth rate of > 15 mm/year, MIB1 expression was significantly increased compared to a control group." (PMID 31291992, 2019).
brain edema (2 papers, 2023 to 2024). Increased intracellular or extracellular fluid in brain tissue. "Brain edema (HR = 12.76, 95% CI = 1.76–92.57, p = 0.012) and MIB-1 index ≥5% (HR = 7.25, 95% CI = 1.11–47.20, p = 0.038) were also found to be significantly associated with shortened PFS." (PMID 37370707, 2023). "Brain edema was observed in 54.2% (13/24) of MSWM patients with an increased MIB-1 index and in fourteen MSWM patients (14/50; 28.0%) of those with a normal MIB-1 index, respectively (p = 0.04)." (PMID 37370707, 2023).
diffuse large B-cell lymphoma (2 papers, 2024). "The histopathology showed tumour cells positive for CD20 and BCL6 with an MIB1 proliferative index of 95%, consistent with a diagnosis of high-grade diffuse large B-cell lymphoma (DLBCL) of the germinal center type." (PMID 39650938, 2024). "Biopsy and pathology analysis revealed a diffuse large B-cell lymphoma (DLBCL), with positive staining for CD20, CD79a, BCL2 and BLC6, but negative for CD10; 30% of the cells were positive for MIB-1 but MUM1 (IRF4) staining was negative, suggesting a germinal center-type lymphoma." (PMID 39110273, 2024).
esophageal squamous cell carcinoma (2 papers, 1996 to 2013). Esophageal squamous cell carcinoma (ESCC) is a type of esophageal carcinoma (EC) that can affect any part of the esophagus, but is usually located in the upper or middle third. "Tumour samples from 150 patients with squamous cell carcinoma of the oesophagus were investigated immunohistochemically with the monoclonal antibody MIB-1, which recognises proliferating cells." (PMID 8855967, 1996).
gastric cancer (2 papers, 1996 to 2017). A primary or metastatic malignant neoplasm involving the stomach. "The prognostic significance of tumour cell proliferation was investigated in a series of 418 gastric carcinomas using the monoclonal antibody MIB-1." (PMID 8795579, 1996). "We examined 106 primary resected gastric cancer patient tissues in a tissue microarray and correlated native-occurring fragments with clinical endpoints, therapeutic targets such as epidermal growth factor receptor (EGFR) and HER2/neu expressions and the proliferation marker MIB1." (PMID 28978092, 2017).
germ cell tumor (2 papers, 2019 to 2020). A benign or malignant, gonadal or extragonadal neoplasm that originates from germ cells. "We aimed to assess the prognostic value of previously suggested biomarkers, related to proliferation (MIB-1 and TEX19) and to immune microenvironment (CXCL12, CXCR4, beta-catenin and MECA-79) in a surveillance cohort of stage I testicular germ cell tumor patients." (PMID 32758242, 2020).
hemangioblastoma (2 papers, 2023 to 2025). "To date, published studies evaluating MIB-1 in hemangioblastomas have included at most 27 cases with immunohistochemical quantification." (PMID 41382243, 2025).
intracranial meningioma (2 papers, 2021 to 2022). A meningioma that arises within the cranial cavity. "Further, we created and evaluated a predictive score for an increased MIB-1 labeling index in sporadic intracranial meningioma." (PMID 34298854, 2021). "The created FORGE score in the present study provides a novel scoring system to predict an elevated MIB-1 labeling index and seems to be useful for predicting tumor recurrence in intracranial meningiomas." (PMID 34298854, 2021).
invasive carcinoma (2 papers, 2016 to 2021). A carcinoma that is not confined to the epithelium, and has spread to the surrounding stroma. "Among invasive carcinomas, 70.8% presented with a low Mib1 proliferative rate, and 8.3% with a special histotype at a very good prognosis (tubular), while 42.8% presented with a Luminal A-like phenotype." (PMID 34203014, 2021). "Among invasive carcinomas, 70.8% presented with a low Mib1, 8.3% with a tubular histotype, and 42.8% with a Luminal A-like phenotype." (PMID 34203014, 2021).
neurocytomas (2 papers, 2022 to 2024). "The proliferation index as evaluated by immunostaining for MIB-1 staining is under 2.3% in classic neurocytomas but over 5.2% in atypical neurocytomas in one study." (PMID 39624201, 2024). "The heterogeneity of these tumors became more apparent upon immunohistochemistry staining, with two tumors (cases 1 and 2) demonstrating high rates of MIB-1 staining for Ki-67 antigen consistent with a diagnosis of atypical neurocytomas." (PMID 35994156, 2022).
neuroendocrine neoplasm (2 papers, 2010 to 2025). Endocrine tumors, also referred to as neuroendocrine tumors (NETs), are defined by a common phenotype which is characterized by the expression of general markers (neuron specific enolase, chromogranin, synaptophysin) and hormone secretion products. "In addition, MIB-1 (Ki-67) has been known as a prognostic indicator in neuroendocrine tumor." (PMID 20444291, 2010).
oligodendroglioma (2 papers, 2013 to 2014). A well-differentiated (WHO grade II), diffusely infiltrating neuroglial tumor, typically located in the cerebral hemispheres. "As an example, in a study on oligodendrogliomas Mcm2 proliferative index (PI) showed good correlation with mitotic index, Ki67/MIB-1 PI, and survival." (PMID 23618321, 2013). "In anaplastic oligodendrogliomas and GBMO, nuclear MIB-1 labeling can be observed in neoplastic cells but also in some histiocytes associated with necrotic areas and some proliferating endothelial cells." (PMID 24949947, 2014).
ovarian carcinoma (2 papers, 2020 to 2023). A malignant neoplasm originating from the surface ovarian epithelium. "In our review, we found that the Ki-67 antigen/MIB-1 antibody immunostaining can be employed as a diagnostic and predictive tool to direct the clinical care of ovarian cancer." (PMID 36768291, 2023). "The Ki-67 antigen/MIB-1 antibody reactive staining, therefore, can be employed as a diagnostic and predictive tool to direct the clinical care of ovarian cancer." (PMID 36768291, 2023).
Salivary Gland Pleomorphic Adenoma (2 papers, 2022 to 2024). A benign, slow-growing tumor composed of cells that demonstrate both epithelial and mesenchymal differentiation. "The objective of this retrospective study was to explore possible changes in histopathological features and expression of cyclin D1 and MIB-1 in salivary gland pleomorphic adenomas (PAs) that recur or undergo malignant transformation." (PMID 35637257, 2022).
Spitz naevus (2 papers, 2025). "Recently, immunohistochemistry studies have been implemented to differentiate the two types of lesions: the Mindbomb Homolog-1 (MIB-1) proliferation marker, for example, has a nuclear proliferation index of 1.5% in Spitz nevus compared to 14.9% in Spitz melanoma." (PMID 41280706, 2025). "When diagnostic uncertainty arose, molecular testing was performed in six cases, for example, testing for MIB-1 to distinguish from Spitz naevus, HMB45 to differentiate from atypical Spitz tumour and S100 to identify spindle cell melanoma from atypical spindle cell tumour." (PMID 40926920, 2025).
triple-negative breast carcinoma (2 papers, 2018). An invasive breast carcinoma which is negative for expression of estrogen receptor (ER), progesterone receptor (PR), and human epidermal growth factor receptor 2 (HER2). "Moreover, CRISPR/Cas9-mediated deletion of MIB1 and MIB2 also sensitized the triple-negative breast cancer cell line MDA-MB-231 to TNF/TAK1i in a RIPK1-dependent manner." (PMID 29642005, 2018). "Furthermore, most patients had ER (71%) and PgR (58.5%) positive status, high MIB1 (57.9%) and HER2/neu negative (50.6%); 10.4% were triple negative breast cancers." (PMID 29716631, 2018).
Ventricular arrhythmia (2 papers, 2021 to 2025). "While QT variability was not increased in Mib1flox;Tnnt2Cre mice, it was elevated in LVNC patients with MIB1 mutations, suggesting a higher risk of ventricular arrhythmias." (PMID 40334239, 2025). "Analysis of QT variability markers revealed elevated values in MIB1 mutation carriers, indicating an increased risk of ventricular arrhythmias." (PMID 40334239, 2025). "Here, we present the case of a patient who came to our attention with a severe LVNC phenotype associated with advanced AV conduction disorder, and supraventricular and ventricular arrhythmias at young age, in which a novel MIB1, likely pathogenic, variation has been identified." (PMID 34564127, 2021).
acromegaly (1 paper, 2022). Acromegaly is an acquired disorder related to excessive production of growth hormone (GH) and characterized by progressive somatic disfigurement (mainly involving the face and extremities) and systemic manifestations. "Patients with an acromegaly had a mean (+/− SD) MIB-1 labeling index of 2.9 +/− 1.4, and those without an acromegaly had a mean (+/− SD) MIB-1 labeling index of 3.1 +/− 1.7, respectively (p = 0.56)." (PMID 36498723, 2022).